INS (insulin)
Diseases named in the same sentence as INS in open-access papers (continued):
Sharing a sentence is not in itself a finding about the gene and the disease.
Alzheimer disease (719 papers, 2006 to 2026). A progressive, neurodegenerative disease characterized by loss of function and death of nerve cells in several areas of the brain leading to loss of cognitive function such as memory and language. "Our review describes the role of insulin in the human brain, as well as the disturbances in insulin signaling resulting from brain insulin resistance, with a particular focus on its association with Alzheimer's disease." (PMID 41683647, 2026). "Blood glucose was significantly increased in patients with Alzheimer's disease, likely reflecting impaired cerebral glucose uptake or insulin signaling, both key mechanisms implicated in Alzheimer's disease pathogenesis." (PMID 41260101, 2025). "The neuroprotective effects of insulin in the brain are compromised, potentially increasing the risk of Alzheimer’s disease and other forms of cognitive impairment." (PMID 40002752, 2025). "The concept of Alzheimer’s Disease as “Type 3 Diabetes” has gained strong scientific support due to the overlap between brain-specific insulin resistance and hallmark AD pathology." (PMID 41003796, 2025). "Although impaired insulin signaling in the brain has been recognized as a key factor in the development and progression of Alzheimer’s disease (AD), the underlying mechanisms remain incompletely understood." (PMID 41280311, 2025). "GLP-1 RAs enhance insulin sensitivity in neurons, counteracting central insulin resistance—an emerging hallmark of Alzheimer’s disease (AD) and Parkinson’s disease (PD)." (PMID 40699685, 2025). "In humans, aberrant INS signaling is the hallmark of metabolic disease, and is thought to play a major role in aging, and age-related diseases, such as Alzheimer’s disease." (PMID 38313028, 2024). "Recent studies have suggested a possible positive outcome of curcumin supplementation on reducing the risk of Alzheimer’s disease through improving insulin sensitivity and consequently deactivating GSK-3." (PMID 38398799, 2024). "Impaired brain insulin signaling can instigate neurocognitive diseases, and impaired glucose uptake is among the hallmark deficits in the Alzheimer’s Disease brain." (PMID 39119146, 2024). "Prolonged intake of HFD induces oxidative stress (OS) that in turn causes neuroinflammation, neurodegeneration, insulin resistance, amyloid burden, synaptic dysfunction and cognitive impairment hence leading to Alzheimer's disease neuropathy." (PMID 39281480, 2024). "The scientific literature undoubtedly links the development of cerebral insulin resistance and hippocampal affection with the risk of developing Alzheimer’s disease." (PMID 39768255, 2024). "Insulin in the brain competes with amyloid-β for insulin degrading enzyme, thus causing Alzheimer’s disease, also known as type 3 diabetes mellitus." (PMID 38534427, 2024). "Impaired insulin signaling and reduced responsiveness are implicated in Alzheimer's disease (AD), mild cognitive impairment (MCI), and other neurodegenerative conditions." (PMID 39073013, 2024). "A study involving amnestic MCI or mild to moderate Alzheimer’s disease (AD) patients found that daily administration of 20 IU regular insulin was associated with better story recall ability compared to the placebo group." (PMID 39220736, 2024). "Several studies have revealed that brain insulin resistance, which means dysregulated brain insulin signaling, is one of the factors of cognitive disorders and Alzheimer’s disease (AD) and is also considered a risk factor for sporadic AD development." (PMID 37664840, 2023). "In particular, the reduction in neuronal insulin signaling seems to underlie the development of cognitive impairments and has been considered a risk factor for Alzheimer's disease (AD)." (PMID 36321333, 2023). "In contrast, in the group with early Alzheimer’s disease, higher insulin was associated with better cognitive performance in attention and verbal memory." (PMID 36900723, 2023).
Alzheimer disease (continued). "We found a protective effect of polygenic risk of higher fasting insulin on Alzheimer’s disease and all-cause dementia (although most of the estimates did not survive Bonferroni correction)." (PMID 37091584, 2023). "There is a mounting body of evidence pointing to a direct association between Alzheimer’s disease (AD) and insulin resistance within brain cells." (PMID 38002034, 2023). "All of these findings are in line with the fact that Alzheimer’s disease is often associated with insulin-deficient and/or insulin-resistant brain states." (PMID 37047558, 2023). "Alzheimer’s disease (AD) is associated with dysregulated pancreatic hormones such as insulin leading to brain insulin resistance that can exacerbate AD pathology." (PMID 37030503, 2023). "Recent studies show that Alzheimer’s disease (AD) has many common links with conditions associated with insulin resistance, including neuroinflammation, impaired insulin signaling, oxidative stress, mitochondrial dysfunction and metabolic syndrome." (PMID 37968954, 2023). "Several studies have documented the association of impaired insulin signalling with protein Aβ and thus Alzheimer’s disease." (PMID 35565918, 2022). "Attenuating acetylcholinesterase and insulin/insulin-like growth factor-1 signaling in the hippocampus is associated with Alzheimer’s disease (AD) development." (PMID 35892598, 2022). "In Alzheimer’s disease, apart from these processes, the alteration of glucose metabolism and insulin signaling in the brain seems to induce early neuronal loss and the impairment of synaptic plasticity, years before the clinical manifestation of the disease." (PMID 36499613, 2022). "Insulin sensitivity, amyloid plaque accumulation, neuroinflammation, and oxidative stress are suggested as important pathogenic mechanisms in Alzheimer disease." (PMID 37551286, 2022). "For two of the three main algorithm variants, runtime on length 2metapaths was measured, using Alzheimer’s disease as a target nodeand a set of three source nodes: insulin, hypothyroidism, and amyloid." (PMID 35936510, 2022). "Disturbed neuronal lipid and cholesterol homeostasis has been linked to central insulin resistance contributing to the pathogenesis of neurodegenerative diseases, such as Alzheimer’s disease (AD)." (PMID 35215406, 2022). "The process of neurodegeneration in Alzheimer’s disease has been associated with a disruption of insulin signaling cascade in neurons, and to insulin resistance." (PMID 35264925, 2022). "A previous study has reported that insulin levels are associated with better cognition in early Alzheimer’s disease." (PMID 35436329, 2022). "Nasal administration of insulin is successfully used as a treatment for Alzheimer’s disease, and type-2 diabetes is associated with the risk of developing Alzheimer’s disease." (PMID 35558436, 2022). "A decrease in insulin release and/or a reduction in its sensitivity, are risk factors in both Alzheimer’s disease (AD) and Parkinson’s disease (PD)." (PMID 36233271, 2022). "The current study further expands our earlier investigation of 20 healthy women at risk for Alzheimer’s disease (AD) in whom higher insulin levels were associated with lower hippocampal-prefrontal resting-state connectivity." (PMID 35492025, 2022). "The mutations in BCL3 have been associated with HDL-C level, fasting insulin level and Alzheimer's disease (AD)." (PMID 33499918, 2021). "Decreased permeation of blood-borne insulin across the blood-brain barrier and decreased signalling in the CNS are associated with Alzheimer's disease." (PMID 34540446, 2021). "Amyloid-beta protein accumulation in the brain caused by high insulin levels, is an early sign of Alzheimer’s disease." (PMID 33958961, 2021). "Changes in CPT activity have been observed in neurological and mental diseases, mainly associated with disturbances in the balance of insulin in the brain, such as Parkinson′s and Alzheimer′s diseases and schizophrenia." (PMID 33466490, 2021).
Alzheimer disease (continued). "Impairments in the regulation of central nervous system (CNS) insulin are associated not only with metabolic syndrome and diabetes mellitus but also with Alzheimer’s disease (AD), age-related cognitive decline, and mild cognitive impairment (MCI)." (PMID 34545146, 2021). "Parkinson’s disease and dementia with Lewy bodies (DLB) frequently overlap with Alzheimer’s disease, which is linked to brain impairments in insulin, insulin-like growth factor, and neurotrophin signaling." (PMID 34576151, 2021). "Progression of Alzheimer’s type of dementia often associates with local insulin resistance; thus, it should be considered as a factor contributing to higher vulnerability of brain to development of Alzheimer’s disease later in the life." (PMID 34572278, 2021). "The brain insulin metabolism alteration has been addressed as a pathophysiological factor underlying Alzheimer’s disease (AD)." (PMID 34948054, 2021). "In this review, we provide an overview of insulin signaling within the brain and the metabolic impact of brain insulin resistance and discuss Alzheimer's disease, one of the neurologic diseases most closely associated with brain insulin resistance." (PMID 33845179, 2021). "It has also been shown to increase the risk of Alzheimer’s disease (AD) by promoting severe neuroinflammation, insulin resistance, synaptic dysfunction, and impairments in cerebral vasculature." (PMID 33435277, 2021). "Alzheimer's disease (AD) is the most common cause of dementia and its development is associated with insulin resistance in the brain." (PMID 32525932, 2020). "The connection between insulin and hippocampal learning and memory processes is further supported by evidence of impaired IR signaling in aging and Alzheimer's disease (AD), two phenotypes that are strongly associated with cognitive decline." (PMID 32852134, 2020). "This research is relevant to both brain trauma and Alzheimer’s disease research as microglia activation and insulin dysregulation have been implicated in their pathology." (PMID 30148836, 2018). "IDE can effectively degrade insulin, amylin, and glucagon, pancreatic hormones that control blood glucose levels, as well as amyloid β (Aβ), a peptide implicated in Alzheimer’s disease." (PMID 29596046, 2018). "This single nucleotide polymorphism (SNP) has been reported to be associated with depression, Alzheimer's disease (AD), hypertension, obesity, Insulin-mediated venodilation, Vasculogenic erectile dysfunction (VED), and functional dyspepsia." (PMID 29416810, 2018). "A number of abnormalities found in Alzheimer’s disease (AD) have also been linked to an insulin resistant state, termed “type 3 diabetes”." (PMID 30534050, 2018). "Alzheimer’s disease (AD) is associated with progressive impairments in brain responsiveness to insulin and insulin-like growth factor (IGF)." (PMID 30705969, 2018). "CPT activity has been associated with dysregulation of insulin equilibrium in brain and related metabolic dysfunctions, and implicated in the evolution of Parkinson's and Alzheimer's diseases." (PMID 27965583, 2016). "Intranasal insulin administration improved memory in young human subjects and in patients with cognitive deficits associated with mild-stage Alzheimer’s disease." (PMID 25889938, 2015). "Impaired insulin transduction aggravates features of Alzheimer's disease including formation of neurofibrillary tangle caused by the decreasing brain glucose level and the increase of amyloid β aggregation." (PMID 24860814, 2014). "In a study in which mice genetically mutated to serve as transgenic mouse models for Alzheimer's disease a tissue-specific decoupling of rapamycin effects were observed when these mice were fed a high sucrose diet and developed insulin resistance." (PMID 25414638, 2014). "Cerebral glucose utilization deficiency and insulin signaling decline are common features between DM and Alzheimer's disease (AD)." (PMID 25197672, 2014).
Alzheimer disease (continued). "There is a large body of evidence linking impaired insulin function and glucose metabolism to the risk of developing Alzheimer’s Disease (AD)-type neurodegeneration." (PMID 24349472, 2013). "Insulin and ghrelin are also implicated in learning/memory, and insulin action is characteristically related to the Alzheimer disease." (PMID 22081645, 2011). "Insulin degrading enzyme (IDE) is responsible for the metabolism of insulin and plays a role in clearance of the Aβ peptide associated with Alzheimer's disease." (PMID 21731629, 2011). "Disrupted insulin/IGF-1 signaling is implicated in Alzheimer's disease, among other conditions, yet its specific influence on glutamate receptor-mediated calcium responses remains unclear." (PMID 41993473, 2026). "In addition, patients with Alzheimer’s disease have abnormal insulin metabolism associated with the apolipoprotein E,33 corroborated by reports of reduced hippocampal insulin-degrading enzyme (an amyloid-β-degrading metalloprotease) in APOE-ε4 carriers." (PMID 40834163, 2025). "Besides anticancer treatment, HDACi is also explored with the suitable therapeutic candidates including rosiglitazone, metformin for the treatment of Alzheimer's disease (AD) implicated by brain insulin signal anomalies." (PMID 39801754, 2025). "Moreover, insulin deficiency also promoted tau hyperphosphorylation in an Alzheimer's disease mice model." (PMID 40296350, 2025). "Neurodegeneration in Alzheimer's disease (AD) is likely associated with disrupted brain glucose metabolism, a well-documented metabolic abnormality that precedes the disease and appears to be influenced by dysfunctional insulin signaling in the AD brain." (PMID 39800464, 2025). "Alterations in ganglioside metabolism contribute to rare hereditary paraplegia, intellectual disability, Alzheimer’s disease (AD), Parkinson’s disease (PD), insulin sensitivity and diabetes, bacterial toxin susceptibility, and severe lysosomal storage diseases." (PMID 41044357, 2025). "Importantly, insulin dysregulation is associated with cognitive disease and disorders, such as Alzheimer’s disease, wherein insulin resistance can exacerbate the accumulation of amyloid-beta plaques and tau tangles." (PMID 39275314, 2024). "This review mainly focuses on epigenetic changes in a few selective genes associated with insulin insensitivity in the periphery and how this peripheral insulin insensitivity is linked with impaired signaling of insulin in the brain, thus causing Alzheimer’s disease." (PMID 38534427, 2024). "Insulin is an important neuroprotective growth factor and neuronal insulin resistance may underlie the link between the presence of metabolic abnormalities and both Alzheimer’s disease and Parkinson’s disease." (PMID 37209215, 2023). "Alzheimer’s disease might be called “type 3 diabetes” because insulin resistance increases the risk of dementia." (PMID 37600514, 2023). "In the prespecified analyses, intranasal insulin treatment using another device was associated with better cognitive function than placebo on the Alzheimer Disease Assessment Scale–Cognitive test (ADAS-Cog12) at 6 months, which strengthened after 18 months of treatment." (PMID 35742986, 2022). "Insulin also can effectively alleviate cognitive dysfunction caused by Alzheimer’s disease." (PMID 36589857, 2022). "Recent studies indicate that ketogenic nutrition targets multiple neurobiological mechanisms associated with the development of Alzheimer’s disease, such as defects in mitochondrial function, cerebrospinal fluid biomarkers, insulin signaling, and dysfunctional glucose and lipid metabolism." (PMID 35065656, 2022). "In recent decades, it has become clearer that peripheral metabolic dysfunction has serious implications for brain health and cognitive function, as insulin resistance and its comorbidities significantly increase the risk of developing Alzheimer’s disease (AD) and other dementias later in life." (PMID 36355101, 2022).
Alzheimer disease (continued). "The abnormality of brain insulin signaling is associated with the aging process and altered brain plasticity, and could promote neurodegeneration in the late stage of Alzheimer’s disease (AD)." (PMID 35055191, 2022). "Taking into consideration that impaired insulin signalling in the brain is heavily associated with Alzheimer’s disease, affecting levels of this hormone may improve a patient’s condition." (PMID 35565918, 2022). "Furthermore, the brain is one of the major sites of insulin action, as such insulin resistance ultimately leads to neuronal cell death causing dementia, Alzheimer’s disease and depression." (PMID 35408607, 2022). "Accordingly, alterations in insulin signaling in the brain can cause brain aging and regulate brain plasticity; therefore, it could promote neurodegeneration in the late stage of Alzheimer’s disease (AD)." (PMID 35055191, 2022). "This suggests that improving insulin sensitivity might be beneficial to patients with brain insulin-resistance associated disorders, such as Alzheimer’s disease, an hypothesis that deserves further experimental studies." (PMID 34209137, 2021). "We assessed the effects of intranasally administered insulin on white matter health and its association with cognition and cerebral spinal fluid biomarker profiles in adults with mild cognitive impairment or Alzheimer's disease in secondary analyses from a prior phase 2 clinical trial (NCT01767909)." (PMID 34101779, 2021). "Indeed, the proposed definition of Alzheimer’s disease as type 3 diabetes (T3D) underlines the key role played by deranged insulin signaling to accumulation of aggregated amyloid beta (Aβ) peptides in the senile plaques of the brain." (PMID 34439505, 2021). "However, one of the studies observed a potential causal associations between insulin sensitivity and Alzheimer’s disease risk and another observed a potential causal association between high plasma glucose and unspecified dementia." (PMID 33868373, 2021). "Furthermore, dysregulation of insulin is involved in the pathogenesis of Alzheimer’s disease, where it is associated with lower levels of insulin in the CSF and with amyloid-beta regulation." (PMID 34834319, 2021). "In view of the close association between insulin resistance and decreased cerebral glucose metabolism with Alzheimer’s disease, it has been argued that Alzheimer’s could be considered as a type 3 diabetes mellitus." (PMID 33567774, 2021). "As a result, patients with impaired insulin metabolism may be at a higher risk of developing Alzheimer’s disease." (PMID 34311759, 2021). "However, in Alzheimer’s disease (AD), mTOR alternately plays important pathogenic roles by inhibiting both insulin signaling and autophagic removal of β-amyloid (Aβ) and phospho-tau (ptau) aggregates." (PMID 34215308, 2021). "Moreover, injections of insulin reversed memory deficits caused by Alzheimer’s disease, and in stroke patients an intranasal insulin treatment has been shown to improve hippocampal-dependent declarative memory in healthy humans." (PMID 33104728, 2020). "Accumulating evidence suggests that Alzheimer’s disease (AD)-related dementia may be associated with brain insulin resistance and deficiency." (PMID 31929603, 2020). "Furthermore, brain insulin resistance caused presumably by vascular insulin resistance is considered to cause Alzheimer’s disease." (PMID 31013778, 2019). "It has also been considered that insulin signaling in the CNS may be involved in declarative memory formation and that the impaired brain insulin signaling plays a critical role in the loss of memory functions associated with Alzheimer’s disease." (PMID 30795555, 2019). "The disclosure of disease-related phenotypes in Epac1/2-/- mice, and the association with insulin secretion and diseases such as Alzheimer’s disease and depression, has prompted considerable efforts to develop compounds that target either Epac1 or Epac2 without affecting PKA signaling." (PMID 30048476, 2018).